CRP (C-reactive protein)
Diseases named in the same sentence as CRP in open-access papers (continued):
Sharing a sentence is not in itself a finding about the gene and the disease.
thyroid cancer (13 papers, 2010 to 2026). "Other studies also confirmed significant positive associations between levels of IL-6 and CRP and thyroid cancer based on a larger population." (PMID 34684331, 2021). "We explored the risk of developing a thyroid cancer by assessing serum biomarkers that are commonly measured in clinical practice and are indicative of inflammation (CRP, albumin, haptoglobin and leukocytes) in a large Swedish cohort study." (PMID 29416653, 2018). "Any CRP levels < 10 mg/L were unquantifiable, which may have resulted in an underestimation of the association with risk of developing a thyroid cancer." (PMID 29416653, 2018). "Generally, in thyroid cancer, there is an increase in inflammatory factors such as Nuclear factor kappa light chain enhancer of activated B lymphocytes (NF-κB) and C-Reactive Protein (CRP), which in turn causes the tumor to progress and worsen the patient’s condition." (PMID 37550760, 2023). "We report a case demonstrating elevations of neutrophil-to-lymphocyte ratio (NLR) and C-reactive protein (CRP) over time as a precursor to anaplastic transformation of thyroid carcinoma." (PMID 39158760, 2024). "Many studies have shown that higher increased levels of IL-6 and CRP, which results in increased FT3 and TT4 levels and increased risk of thyroid carcinoma." (PMID 39764244, 2024). "White blood cell counts, but not serum CRP concentrations, were also positively associated with thyroid cancer risk by 1.38 times." (PMID 33805984, 2021). "Moreover, thyroid cancer patients exhibited higher levels of RDW, hs-CRP, HbA1c, and ALS, along with lower levels of MCHC (all P < 0.05)." (PMID 41569987, 2026).
thyrotoxicosis (13 papers, 2021 to 2024). A hypermetabolic syndrome caused by the elevation of thyroid hormone levels in the serum. "Laboratory examination showed high C-reactive protein levels, with elevated erythrocyte sedimentation rate, and thyroid function tests were suggestive of thyrotoxicosis." (PMID 38374864, 2024). "Blood chemistry tests revealed thyrotoxicosis and elevated serum C-reactive protein (CRP) and slightly increased serum antithyroid-stimulating antibody (TSAb) levels." (PMID 36879263, 2023). "The patient was diagnosed with SAT because of severe tenderness at the thyroid gland site, elevated CRP levels, findings indicating thyrotoxicosis in thyroid function tests, and SAT-related findings during ultrasonography." (PMID 36879263, 2023). "Blood chemistry tests revealed thyrotoxicosis and elevated serum CRP, TSAb, and antithyroid-stimulating hormone receptor antibody levels." (PMID 36879263, 2023). "Laboratory tests ordered were consistent with SAT and included accelerated ESR, elevated CRP, and thyrotoxicosis in the thyroid function test." (PMID 35813005, 2022). "Other laboratory findings included thyrotoxicosis (free T3: 9.13 pg/mL; free T4: 3.64 ng/dL; and thyroid-stimulating hormone (TSH): <0.01 μIU/mL) and a high C-reactive protein (CRP) level (3.84 mg/dL)." (PMID 39447604, 2024). "The laboratory results on day 0 revealed thyrotoxicosis (FT3: 9.13 pg/mL; FT4: 3.64 ng/dL; and TSH: <0.01 μIU/mL and a high CRP level (3.84 mg/dL)." (PMID 39447604, 2024). "Laboratory findings confirm thyrotoxicosis (suppressed TSH, high FT4) and inflammatory markers, i.e., ESR and CRP, are typically elevated." (PMID 36394704, 2023). "We suggest monitoring the initial T3 and CRP levels with subsequent confirmation of TBII and TgAb in the differential diagnosis of thyrotoxicosis." (PMID 35741278, 2022). "We suggest monitor the initial T3 and CRP levels with subsequent confirmation of TBII and TgAb in the differential diagnosis of thyrotoxicosis." (PMID 35741278, 2022). "Laboratory results typically show a state of thyrotoxicosis, with negative TPO antibodies, as well as increased C-reactive protein (CRP) and erythrocyte sedimentation rate." (PMID 39967901, 2024). "In a patient with thyrotoxicosis, in the absence of painful and tender thyroid, nor elevated ESR and CRP, a T3/fT4 ratio of 25 would favor GD diagnosis versus SAT." (PMID 39055454, 2024).
urolithiasis (13 papers, 2015 to 2025). Stone(s) within the urinary tract. "The modified STONE scoring system incorporates five clinical parameters gender, duration of pain, hematuria, history of urinary stones, and C-reactive protein (CRP) levels to improve diagnostic precision." (PMID 41150170, 2025). "Several studies have been conducted to investigate the associations between the risk of developing urinary stones and inflammatory markers, including CRP concentrations, the NLR, the MLR, and the SII." (PMID 40075397, 2025). "Moreover, data on the relationship between the risk of developing urinary stones and inflammatory markers other than CRP are scarce." (PMID 40075397, 2025). "CRP levels were significantly higher in patients with urolithiasis treated with URS treatment compared to those treated with ESWL on the first post-intervention day and after six months." (PMID 38327930, 2024). "CRP levels on the pre-intervention measurement day significantly increased on the first post-intervention day in patients with urolithiasis treated with both ESWL and URS treatment." (PMID 38327930, 2024). "In dogs with gastric dilatation, gastric volvulus and urolithiasis CRP was within the normal range, but other authors report a significant increase in CRP concentration 24 and 48 h after the gastric dilatation-volvulus surgery." (PMID 36290272, 2022). "However, there was no causal association between other common risk factors (PTH, CRP, IL6, IL18, IL27, IL8, IL16, IL1Ra, coffee consumption, age of smoking initiation, smoking initiation, and cigarettes smoked per day) and urolithiasis in the meta-analysis." (PMID 37624788, 2023). "Additionally, Hasna and colleagues (2015) found that diabetic patients with urolithiasis were characterised by higher CRP and IL-6 levels than diabetes mellitus cases without urolithiasis." (PMID 34440695, 2021). "In the univariate analysis, there were significant differences between groups with urosepsis and nonurosepsis in history of urolithiasis surgery, PUC+, urine WBC+, NIT+, urine bacterial count, Cys-C, GFR, PCT, CRP, D2-F, WBC, NEUT%, and PLT." (PMID 35309171, 2022).
venereal disease (13 papers, 2018 to 2025). "Laboratory parameters included complete blood cell (CBC), erythrocyte sedimentation rate (ESR), C-reactive protein (CRP), and venereal disease research laboratory (VDRL)." (PMID 32228711, 2020).
asthenia (12 papers, 2017 to 2025). Clinical sign or symptom manifested as debility, or lack or loss of strength and energy. "The most important differences regarded the Apache II score, Glasgow Coma Score (GCS), CRP (C-reactive protein), pH, creatinine, RR (respiratory rate), and asthenia." (PMID 32838194, 2020). "Moreover, we found that lymphocytes and ALT levels correlate positively with the presence of asthenia or fatigue at 4–6 weeks; meanwhile CRP, troponin, resistin, IL-8 and MCP-1 levels correlate negatively (data not shown)." (PMID 35330391, 2022). "On May 5, 2002, the patient presented with chills and asthenia, without fever or other associated symptoms, with a biological inflammatory syndrome (his C-reactive protein (CRP) level was 61 mg/L)." (PMID 40115698, 2025). "The main manifestations of LV-GCA are constitutional symptoms (asthenia, anorexia, weight loss, unexplained fever) and nonspecific increase in acute phase reactants (erythrocyte sedimentation rate [ESR] and C-reactive protein [CRP])." (PMID 35159949, 2022).
cerebral small vessel disease (12 papers, 2014 to 2025). Cerebral small vessel disease is the term currently used to pathological processes that affect the brain parenchymal circulation (arterioles, capillaries, and veins). "Clinically, HsCRP is more sensitive than CRP and is closely associated with cerebral small vessel disease." (PMID 38903919, 2024). "Strength of our study includes simultaneous measurement of inflammatory biomarker CRP and white matter damage as assessed by CT scan in a population of high risk for small vessel cerebrovascular disease." (PMID 24587705, 2014). "There were studies showed that CRP concentrations were associated with white matter lesions, suggesting inflammatory process involvement in the pathogenesis of cerebral small vessel disease." (PMID 25191699, 2014). "Moreover, a recent study revealed that higher CRP levels were associated with subclinical markers of cerebral small vessel disease and neurodegeneration." (PMID 30808986, 2019). "Studies showed that if the level of CRP is associated with cerebral small vessel disease, this protein might be utilized as a useful marker for monitoring the risk of cerebral small vessel disease-related brain lesions." (PMID 24587705, 2014). "Elevated CRP levels have been correlated with brain structural changes and the imaging markers of cerebral small vessel disease, as well as neurodegeneration." (PMID 40427506, 2025). "Some studies showed that systemic inflammatory processes, which include high levels of CRP, are related to the pathogenesis of cerebral small vessel disease at the development of cerebral WML and lacunar infarcts." (PMID 24587705, 2014). "We investigated the relationship between lymphocyte-to-C-reactive protein ratio (LCR) and common imaging markers of cerebral small vessel disease (CSVD)." (PMID 39777309, 2024). "A recent systematic review analyzed the role of vascular (e.g. VWF, homocysteine) and systemic (e.g. CRP, IL-6) inflammatory biomarkers in relation to cerebral small vessel disease (SVD) in a non-CKD population." (PMID 35042473, 2022). "In addition, a recent study suggested that the relationships of ALP and CRP were independent of each other in cerebral small vessel disease and that ALP was still significantly related to WMH volume after adjusting the renal function and excluding subjects with impaired kidney function." (PMID 37181626, 2023).
chronic pancreatitis (12 papers, 2016 to 2025). A chronic inflammatory process causing damage and fibrosis of the pancreatic parenchyma. "CRP levels can be higher in patients with chronic pancreatitis and type 2 DM than those with isolated chronic pancreatitis, and also, an inverse correlation has been reported for CRP and subjects with alcoholic chronic pancreatitis." (PMID 37873776, 2023). "In one case (age group 12–19 years), septic complications (fever, elevation of C-reactive protein) developed after insertion of a pancreatic stent in a patient with chronic pancreatitis and pancreaticolithiasis." (PMID 30653580, 2019). "TNF-α and C-reactive protein indices were higher in patients with chronic pancreatitis and T2DM than those with isolated chronic pancreatitis, characterizing the persistence of chronic systemic inflammation in case of the combined clinical course of these diseases." (PMID 33456608, 2020). "In the chronic pancreatitis group, the mean values of GGT, ALP and CRP were significantly higher, but total transferrin was significantly lower in the CP group than that in the controls." (PMID 35329964, 2022). "Additionally elevated levels of WCC, amylase, lipase, C-reactive protein (CRP), procalcitonin, AST, ALT, total bilirubin, and conjugated bilirubin have been reported in the context of acute and chronic pancreatitis have been reported." (PMID 40731941, 2025). "CA 19–9, carcinoembryonic antigen (CEA), C-reactive protein, albumin, insulin growth factor-1 (IGF-1) and IGF binding protein-3 were measured using routine clinical analyzers in a cohort of 47 pancreatic adenocarcinoma, 20 chronic pancreatitis and 15 healthy controls." (PMID 26808421, 2016).
dermatomyositis (12 papers, 2012 to 2025). Dermatomyositis (DM) is a type of idiopathic inflammatory myopathy characterized by evocative skin lesions and symmetrical proximal muscle weakness. "Although CRP can be elevated in dermatomyositis, as few data demonstrate, it can be less than 1 mg/L during childhood dermatomyositis." (PMID 37873776, 2023). "We developed a cluster model consisting of 6 clusters, which were categorized by age at onset, clinically amyopathic dermatomyositis, CRP, KL-6, requirement of supplemental oxygen, anti-ARS antibody, and anti-MDA5 antibody." (PMID 35615085, 2022). "Cluster 2 (n = 72, 44.4%) grouped patients with dermatomyositis-specific rash, arthralgia, ILD and increased ESR or CRP levels." (PMID 38522973, 2024). "Furthermore, in patients with dermatomyositis, serum resistin levels significantly correlated with MYOACT (r = 0.667, P = 0.001), creatine kinase (r = 0.739, P = 0.001) and myoglobin levels (r = 0.791, P = 0.0003) and showed a trend towards correlation with CRP levels (r = 0.447, P = 0.067)." (PMID 22577940, 2012).
eczema (12 papers, 2009 to 2024). "A month later, he developed eczema and chronic diarrhea that was associated with increasing CRP values and elevated fecal calprotectin." (PMID 39247195, 2024). "During treatment of eczema with LGG, we found a significant increase in blood concentration of C-reactive protein (CRP) in infants having had a favorable clinical effect, in those with IgE-associated eczema." (PMID 23283013, 2009).
enteritis (12 papers, 2014 to 2025). Inflammation of the small intestine. "Comparisons of WBC values and CRP, which indicate inflammation, showed significantly higher CRP values in the enteritis group (P= 0.01)." (PMID 40230560, 2025). "In our patients, at least one of these systemic signs (fever, elevated white blood cell count, or increased CRP level) was observed, suggesting their potential utility as useful markers in the differential diagnosis of pediatric enteritis." (PMID 41001291, 2025). "At that time, although C-reactive protein levels were markedly elevated (25 mg/dL), the clinical symptoms and imaging findings of enteritis were mild, and the patient was treated with a 5-day course of intravenous cefazolin before being discharged." (PMID 41278405, 2025). "C-reactive protein (CRP) level (mg/dL) was significantly higher in the enteritis group (1.57 vs. 0.69,P= 0.01)." (PMID 40230560, 2025). "In the CMV enteritis group, a significantly higher proportion of patients developed fever and GI bleeding in combination with higher CRP and lower Hb levels, indicating more severe mucosal injury and inflammation, than that in the non-CMV group." (PMID 34407879, 2021). "The mean CRP was significantly higher in the group with enteritis compared to the AA group, p = 0.03." (PMID 28033410, 2016). "Blood tests revealed higher C-reactive protein (CRP) levels in the enteritis group (P< 0.01)." (PMID 40230560, 2025). "By the end of the first 3 weeks of eculizumab treatment, the abdominal pain and enteritis had completely resolved, levels of CRP had fallen to zero, LDH concentration and D-dimer were within the normal range, and levels of platelets and hemoglobin were increasing." (PMID 24587926, 2014). "Using the DSS enterocolitis mouse model, the expression of SAA1-4 and CRP was evaluated in the liver and several parts of the intestinal tract to determine the main organ of SAA expression in enteritis." (PMID 35303008, 2022). "Blood tests gave indications of inflammation with elevated C-reactive protein (CRP) (99.6 mg/L; upper limit of normal (ULN) 6 mg/L) and suspicions of enteritis." (PMID 24587926, 2014).
fracture (12 papers, 2016 to 2025). "According to a recent report, the CAR can help predict the risk of postoperative death in elderly patients with hip fracture, and the combination of CRP and Alb with POD was more likely to reflect preexisting inflammatory stress than CRP or Alb alone." (PMID 36051706, 2022). "Four of the 14 studies, involving 1238 patients with hip fracture, compared preoperative CRP levels between the death and survival groups for a follow-up duration of ≤ 30 days." (PMID 36894998, 2023). "Eight of the included 14 studies, involving 2361 patients with hip fracture, compared preoperative CRP levels between the death and survival groups for a follow-up duration of ≥ 6 months." (PMID 36894998, 2023). "Regarding the prognostic role of CRP in hip fracture, numerous studies have reported a correlation between higher perioperative CRP level and higher mortality rate in patients following hip fracture surgery; however, some studies did not report such a correlation." (PMID 36894998, 2023). "The aim of this study is to evaluate a predictive score of mortality after hip fracture in older persons on the basis of the objective prognostic factors easily available: age, sex and neutrophil-to-lymphocyte ratio (NLR) and C-reactive protein (CRP)." (PMID 27230508, 2016).
glaucoma (12 papers, 2012 to 2025). Increased pressure in the eyeball due to obstruction of the outflow of aqueous humor. "Alterations in the levels of CRP and interleukin-6 (IL-6) in glaucoma, along with their associations with the disease, warrant further investigation." (PMID 40440644, 2025). "Interleukin-6 (IL-6) has a major role in the pathology of glaucoma, among other systemic inflammatory diseases, and high plasma C-reactive protein (CRP) levels have been associated with normal tension glaucoma." (PMID 35215429, 2022). "Moreover, MetS and its components, as well as CRP, a marker of inflammation, have been associated with retinal diseases including age‐related macular degeneration, retinopathy, and glaucoma, resulting in significant increases in morbidity and mortality." (PMID 36919192, 2023). "However, C-reactive protein (CRP) did not have a strong association with glaucoma in our study." (PMID 39967596, 2025). "For glaucoma, PTGDS, GSTP1, SPD1, and CST3 were expressed significantly higher in almost all tissues; CRP, ALB, and TTR were markedly increased in the liver; MBP and TF exhibited high expression in the brain." (PMID 37052519, 2023). "However, a large population-based Chinese cohort study could not find any association between the different glaucoma phenotypes and systemic inflammation, as depicted by C-reactive-protein values." (PMID 33032589, 2020). "NTG as a subtype of primary open angle glaucoma (POAG) is related to several conditions such as nocturnal hypotension, inflammatory diseases and C-reactive protein (CRP) alterations." (PMID 31788489, 2019). "Consistent with mass spectrometry findings, we observed that A2M, B2M, Clusterin, TNC, FVII, Adiponectin, CRP, SAA, ICAM-1 and VCAM-1 were differentially affected in the retinas and vitreous of glaucoma subjects." (PMID 28978942, 2017).
hearing loss (12 papers, 2016 to 2026). "The results of this study were confirmed in the “Epidemiology of Hearing Loss Study,” which found an association of elevated CRP levels at baseline and future development of SNHL." (PMID 31781229, 2019). "Additionally, a cross-sectional study found that lipid and C-reactive protein levels are risk factors for hearing loss in older adults, with high dietary cholesterol intake increasing the risk of hearing loss." (PMID 39677857, 2024). "We report a pediatric case who had had persistently elevated serum C-reactive protein (CRP) level since infancy and was diagnosed with MWS by the development of sensorineural hearing loss in school age." (PMID 36873639, 2023). "Serum concentrations of TNF-α and C-reactive protein (CRP) are significantly increased in people with hearing impairment under the age of 60." (PMID 34320993, 2021). "Overall, by analyzing the sensitivity and specificity of CRP, IIS, NLR, and PLR in the same hearing loss disease and cohort, we can gain a more comprehensive understanding of the role of systemic inflammation in the development of hearing loss." (PMID 38715688, 2024).